MBD2 (methyl-CpG binding domain protein 2)
Diseases named in the same sentence as MBD2 in open-access papers (continued):
Sharing a sentence is not in itself a finding about the gene and the disease.
asthma (continued). "Compared to the T2 asthma group, the expression of MBD2 protein and mRNA in lung tissues and BECs from the Th17-dominant asthma group was significantly increased, while the corresponding expression of MINK1 mRNA and protein was significantly impaired." (PMID 36303542, 2022). "We performed in vitro splenocyte tests to determine if MBD2 is involved in the development of severe asthma and discovered that IL-17 protein expression dramatically increased along with MBD2 overexpression and decreased with MBD2 silencing." (PMID 36062195, 2022). "We also found the increased MBD2 expression after stimulus differentiation in splenic CD4+ T-cells in our animal model, showing involvement of MBD2 in immunological pathogenesis of Th17 mediated neutrophilic severe asthma and differentiation of CD4+ T-cells." (PMID 35096261, 2021). "This shows that androgen possibly affects downregulation of Th17 via MBD2 in BECs, showing BECs as a cellular target in treating severe asthma." (PMID 35096261, 2021). "Serum MBD2 levels were higher in patients with Th17 severe asthma compared to those with T2 severe asthma." (PMID 34692717, 2021). "The MBD2 and Th17 expression is directly correlated, while male sex hormone is inversely correlated with MBD2 and Th17 in severe asthma." (PMID 35096261, 2021). "A higher MBD2 level is associated with the pathogenesis of severe asthma (non-T2), as shown from different studies, and MBD2 regulates the expression of Th17 cells in severe asthma." (PMID 35096261, 2021). "The mechanism of MBD2 regulation of Th2 cell function and eosinophilic inflammation in asthma needs to be further elucidated." (PMID 34692717, 2021). "In this study, we confirmed that MBD2 is expressed in the serum of patients with asthma, suggesting that MBD2 is involved in the development of asthma." (PMID 34692717, 2021). "In this study, we found that serum MBD2 levels were increased in patients with severe asthma compared to those with asthma and HCs, as well as in asthma patients compared to HCs." (PMID 34692717, 2021). "Our initial study in patients showed increased expression of MBD2 in Th17 mediated severe asthma from peripheral blood samples." (PMID 35096261, 2021). "Our recent study showed the potential role of MBD2 as a novel biomarker for identifying severe asthma various endotypes." (PMID 35096261, 2021). "The objective of this study was to investigate the relationship between serum MBD2 levels in patients with severe asthma with different endotypes." (PMID 34692717, 2021). "Another study found that MBD2 was significantly elevated in mice with neutrophils-dominant asthma compared to mice with conventional asthma and the control group." (PMID 34692717, 2021). "MBD2 was also significantly increased in patients with Th17 severe asthma compared to patients with type 2 severe asthma." (PMID 34692717, 2021). "MBD2 is an important mediator in Th17 predominant neutrophilic severe asthma pathogenesis and is justified by different studies." (PMID 35096261, 2021). "MBD2 and HIF-1α genes were silenced or overexpressed through lentiviral transduction to explore the roles of MBD2 in Th17 cell differentiation and IL-17 release in neutrophils-dominant asthma." (PMID 30150897, 2018). "Histological analyses of lungs from the neutrophils-dominant asthma group showed more abundant cells with MBD2 compared to the conventional asthma group." (PMID 30150897, 2018). "Our findings uncover new roles for HIF-1α and MBD2, and provide novel insights into the epigenetic regulation of neutrophils-dominant asthma." (PMID 30150897, 2018). "Our study suggested that MBD2 regulates Th17 cell differentiation and IL-17 expression in neutrophils-dominant asthma through HIF-1α." (PMID 30150897, 2018). "Our previous studies indicated that Methtyl-CpG binding domain protein 2 (MBD2) expression was increased in asthma patients." (PMID 30150897, 2018).
asthma (continued). "Methyl-CpG binding domain protein 2 (MBD2) expression increased in CD4+ T cells in peripheral blood samples of asthma patients." (PMID 28808358, 2017). "Through these tests, MBD2 is shown to participate in severe asthma by affecting the differentiation of Th17 cells and IL-17 secretion." (PMID 28808358, 2017). "The lung is one of the effector organs of immunity, and MBD2 showed a higher expression in the lung tissue of severe asthma model mice compared with the conventional asthma model mice." (PMID 28808358, 2017). "In our study, MBD2 showed significantly increased expression in the splenocytes of the severe asthma model mice, representing the classical observation target as immune cells." (PMID 28808358, 2017). "Additionally, MBD2 influenced the overexpression of miR-146a-3p, which inhibited the in vivo response of Th17 cells and alleviated severe asthma." (PMID 40533455, 2025). "However, the specific role of MBD2 in macrophage polarization during asthma progression remains poorly understood." (PMID 40533455, 2025). "Moreover, exposure to HDM and LPS enhances MBD2 binding to the promoter region of the MINK1 gene, showing that MBD2 is the factor silencing MINK1 in Th17-dominant asthma." (PMID 39727954, 2024). "Interestingly, we found that the relative miR-146a-3p levels were markedly decreased in PBMCs, while MBD2 protein expression levels were increased in the serum of severe asthma patients, which is consistent with our previous research." (PMID 36961677, 2023). "Although our previous study found that MBD2 plays an important role in the pathogenesis of severe asthma and MBD2-KO significantly ameliorated severe asthma, MBD2 upstream epigenetic regulation in severe asthma remains unknown." (PMID 36961677, 2023). "Taken together, these data indicated that miR-146a-3p might be a potential novel therapeutic by targeting MBD2 in Th17 cell-mediated severe asthma." (PMID 36961677, 2023). "Furthermore, we show that the inhalation of miR-146a-3p agomir suppresses the development of airway inflammation and relieves the severe asthma mouse model in vivo by decreasing MBD2 expression." (PMID 36961677, 2023). "Finally, we constructed a mouse model of Th17 predominant neutrophilic severe asthma to assess the therapeutic potential of miR-146a-3p in severe asthma and the effect of miR-146a-3p regulated Th17 cells differentiation via MBD2 in vivo." (PMID 36961677, 2023). "Collectively, our data revealed that Mbd2 implicates in the pathogenesis of asthma predominantly by regulating the polarization of M2 macrophages, which supports that Mbd2 could be a viable target for treatment of asthma in clinical settings." (PMID 36090987, 2022). "Methyl-CpG-binding domain protein 2 (MBD2) is a critical player in asthma epigenetics and immunity that determines the transcriptional state of the epigenome, interprets DNA methylation marks, induces posttranscriptional histone modification, and regulates the target genes." (PMID 36062195, 2022). "Here, we evaluate whether sex hormones (androgen) can offer a novel potential therapeutic role in the treatment of Th17 cells predominant neutrophilic severe asthma through regulating MBD2 expression." (PMID 36062195, 2022). "In fact, Mbd2 may also be involved in the pathogenesis of asthma by regulating dendritic cell functions and Th17 differentiation." (PMID 36090987, 2022). "Considering the role of Th17 cells in glucocorticoid-insensitive asthma, MBD2 may be involved in the pathogenesis of Th17-dominant asthma." (PMID 36303542, 2022). "Thus, silencing or OE of MBD2 corresponds with the MBD2 detection in the respective groups, and DHT decreases MBD2 expression in severe asthma." (PMID 36062195, 2022). "To verify that MBD2 is involved in Th17-dominant asthma, we performed an in vitro study on BECs." (PMID 36303542, 2022).
asthma (continued). "However, OE-MBD2+E2 was associated with higher Th17 cells differentiation than the OE-MBD2 of severe asthma showing Th17 cells differentiation was MBD2 dependent." (PMID 36062195, 2022). "However, our data renewed the understanding of Mbd2 in the polarization of macrophages during asthma progression." (PMID 36090987, 2022). "Androgen attenuated the differentiation of BECs regulated Th17 cells via MBD2 showing BECs as a therapeutic target of androgen, and these findings postulate the novel role of androgen in Th17 cells predominant neutrophilic severe asthma therapy through targeting MBD2." (PMID 36062195, 2022). "Our previous studies showed that methyl-CpG binding domain protein 2 (MBD2) expression was significantly increased in patients with Th17 severe asthma and could regulate Th17 cell differentiation." (PMID 36303542, 2022). "At present, Th17-mediated asthma is more likely to develop into severe asthma due to poor response to glucocorticoids, and MBD2 may also have a potential therapeutic effect on severe asthma." (PMID 36303542, 2022). "Collectively, these results not only demonstrate a role for Mbd2 in asthma pathogenesis, but also support that MBD2 could be a viable target for prevention and treatment of asthma in clinical settings." (PMID 36090987, 2022). "Together, our data provided experimental evidence supporting that Mbd2 could be a viable target to prevent/treat asthma in clinical settings." (PMID 36090987, 2022). "MBD2 increases HIF-1α in neutrophil-dominant asthma and is involved in increased differentiation and secretion of Th17 cells and IL17 through regulating the HIF-1α expression and also reduces the Treg function through an increase in HIF-1α suggesting the epigenetic role of MBD2 in severe asthma." (PMID 35096261, 2021). "It is worth noting that MBD2 is involved in the differentiation and expression of Th17 and its asthma-related inflammatory cytokines via inducing epigenetic changes through different mechanisms, and MBD2 itself and/or MBD2 mediated Th 17 cells can be a potential therapeutic target in severe asthma." (PMID 35096261, 2021). "What is the influence of sex hormones in MBD2 mediated Th17 predominant severe asthma?" (PMID 35096261, 2021). "In addition, we found that MBD2 was significantly increased in severe asthma, especially the Th17 endotype, compared to HCs and patients with mild to moderate asthma." (PMID 34692717, 2021). "Recently, our study found that methyl CpG binding domain protein 2-mediated Th17 differentiation in severe asthma is associated with IRF4 and SOCS3 expression, providing novel insight into epigenetic regulation and target for treatment in severe asthma." (PMID 34566492, 2021). "The study also postulated MBD2 regulated Th17 differentiation is mediated via affecting the expression of an interferon regulatory factor 4, needed for developing inflammatory Th17 cells in severe asthma." (PMID 35096261, 2021). "Does androgen downregulate the MBD2 expression in severe asthma ?." (PMID 35096261, 2021). "In conclusion, serum MBD2 may be a potential new biomarker for identifying severe asthma, Th17 severe asthma and the type of airway inflammation." (PMID 34692717, 2021). "A study has shown that MBD2 gene silencing significantly lowers the IL-17 expression as increased expression increases the IL-17 expression from splenic CD4+ T cells in an animal model of asthma." (PMID 35096261, 2021). "MBD2 deficiency attenuates the TGF-β1 production with decreased M2 macrophage gathering in bleomycin-induced lung fibrosis, and M2 polarized macrophages are correlated with FEV1 in asthma." (PMID 35096261, 2021). "However, little is known about that epigenetic regulation of MBD2 in both immunological pathogenesis of experimental severe asthma and CD4+ T cell differentiation." (PMID 28808358, 2017). "This shows that MBD2 can affect IRF4 expression in severe asthma." (PMID 28808358, 2017).
asthma (continued). "Notably, peripheral blood analysis in asthma patients revealed a correlation between serum MBD2 levels and Th17 cell populations, suggesting that MBD2 expression could serve as a biomarker for asthma endotypes." (PMID 41008562, 2025). "Furthermore, patients with severe asthma exhibited significantly higher MBD2 levels compared to those with mild to moderate disease and healthy controls, indicating a strong correlation between MBD2 expression and asthma severity." (PMID 41008562, 2025). "However, the role of miR-146a-3p in the differentiation of Th17 cells via MBD2 in severe asthma remains unknown." (PMID 36961677, 2023). "Firstly, although we have revealed the role of MBD2 regulating M2 polarization in the development of asthma, and our previous study showed the Mbd2 enhances PI3K/Akt signaling to promote macrophage M2 program, other mechanisms between Mbd2 and macrophage polarization are still remain unknown." (PMID 36090987, 2022). "Therefore, we hypothesized that androgen has a potential therapeutic role in MBD2-mediated Th17 cells predominant neutrophilic severe asthma." (PMID 36062195, 2022). "MBD2 binds to the target gene′s promoter region, induces posttranscriptional histone modification, changes the chromatin structure, and ultimately regulates the expression of target genes, and this is believed to be an essential critical mediator in asthma epigenetics mechanism." (PMID 35096261, 2021). "This review briefly overviews the sex hormones, their influence in asthma at the different physiobiological conditions of human body, and MBD2 severe asthma connection with the possible therapeutic potential of sex steroids in MBD2 mediated Th17 predominant severe asthma." (PMID 35096261, 2021). "MPO is a marker of neutrophil activity, and the correlation analysis suggested that MBD2 might be involved in the development of asthma by mediating the differentiation of Th17 cells, which secrete the cytokine IL-17A to chemotactic neutrophils into the airway and causing chronic inflammation." (PMID 34692717, 2021). "Therefore, MBD2 may have a close relationship with the immunological pathogenesis of asthma and contribute to Th17 cell differentiation and IL-17 expression through HIF-1α." (PMID 30150897, 2018). "MBD2, as an epigenetic regulation element, can regulate T cells to differentiate into Th17 cells by methylating T-bet/Hlx, so it could be involved in the pathogenesis of severe asthma." (PMID 28808358, 2017). "Therefore, MBD2 could play an important role in neutrophil-predominant severe asthma, and to find which cytokine it impacts is our next research goal." (PMID 28808358, 2017). "Methyl-CpG-binding domain protein 2 (MBD2), a “reader” protein, recognizes methylated CpG sites, while the DNA demethylating enzyme TET1 functions as an “eraser” in asthma." (PMID 41008562, 2025). "In addition, Binaya Wasti and her team found that sex hormones, especially androgens, can inhibit Th17 cell differentiation by targeting Methyl‐CpG‐binding domain protein 2 (MBD2), which could potentially play a novel hormonal therapeutic role in Th17 cell‐dominated neutropenic severe asthma." (PMID 39800672, 2025). "Methyl-CpG binding domain protein 2 (MBD2) regulates the differentiation of the Th17 cells, tending to show a therapeutic target in severe asthma." (PMID 36961677, 2023). "The effect of DHT and E2 on MBD2, Th17 cells (IL17), and RORγt was also explored in animal and cellular model of asthma." (PMID 36062195, 2022). "Our findings have revealed new roles for MBD2 and MINK1 and provide new insights into epigenetic regulation of Th17-dominant asthma, which is dominated by neutrophils and Th17 cells." (PMID 36303542, 2022). "Together, these data indicated that MBD2 induced Th17 cell differentiation by maintaining MINK1 silencing, thereby contributing to the development of Th17-dominant asthma." (PMID 36303542, 2022).
asthma (continued). "In this study, we found that serum MBD2, ECP and MPO levels and the percentage of Th2 cells in the peripheral blood was higher in patients with asthma and in those with T2 severe asthma." (PMID 34692717, 2021). "In a study, MBD2 downregulated the SOCS3 expression and promoted the differentiation of Th17 cells in severe asthma, showing its involvement in Th17 mediated neutrophilic predominant severe asthma." (PMID 35096261, 2021). "Therefore, we hypothesized that MBD2 might be a potential biomarker for Th17 severe asthma." (PMID 34692717, 2021). "Methyl-CpG binding domain protein 2 (MBD2) is overexpressed and regulates the Th17 differentiation, showing the possibility of therapeutic target in treating Th17 mediated severe asthma." (PMID 35096261, 2021). "Our findings have uncovered new roles for MBD2 and HIF-1α, and provide novel insights into the epigenetic regulation of neutrophils-dominant asthma." (PMID 30150897, 2018). "Our previous work indicates that, compared to healthy volunteers, MBD2 and HIF-1α expression in CD4+ T cells was increased in the peripheral blood of patients with asthma." (PMID 30150897, 2018). "MBD2 and HIF-1α expression were significantly increased in the lung and spleen cells of mice with neutrophils-dominant asthma." (PMID 30150897, 2018). "The aim of the present study is to understand how MBD2 interacts with HIF-1α to regulate Th17 cell differentiation and IL-17 expression in neutrophils-dominant asthma." (PMID 30150897, 2018). "MBD2 expression in lung and splenic CD4+ T cells from the neutrophils-dominant asthma group were significantly increased compared to the conventional asthma group." (PMID 30150897, 2018). "A neutrophils-dominant asthma mouse model was established using female C57BL/6 mice to investigate Th17 cell differentiation and MBD2 and HIF-1α expression regulation using flow cytometry, western blot or qRT-PCR." (PMID 30150897, 2018). "To ascertain whether MBD2 is involved in the pathogenesis of severe asthma, we conducted in vitro splenocyte experiments and found that IL-17 protein expression increased significantly along with overexpression of the MBD2 gene and decreased with the silencing of the MBD2 gene." (PMID 28808358, 2017). "Silencing of MBD2 decreased the detection of RORγt in severe asthma significantly but not GATA3 which was counter confirmed by SiR-NC-MBD2." (PMID 36062195, 2022). "Taken together, these data suggested that MBD2 might promote Th17 cell differentiation by inhibiting MINK1, thereby exacerbating the severity of asthma." (PMID 36303542, 2022). "In this study, we aimed to determine the role of MBD2 and MINK1 in Th17-dominant asthma." (PMID 36303542, 2022). "At present, we do not know the role of sex hormones especially in MBD2-mediated Th17 cells predominant neutrophilic severe asthma." (PMID 36062195, 2022). "Thus, the increased expression of MBD2, Th17 cells (IL17), and RORγt in severe asthma was perceived." (PMID 36062195, 2022). "The epigenetic regulatory mechanisms of asthma include DNA methylation, and the methyl-CpG binding domain (MBD) family of proteins play a “reader” and regulatory role as a key bridge in the process of DNA methylation, and MBD2 is a member of the family." (PMID 36303542, 2022). "Furthermore, MBD2 was positively correlated with MPO and Th17 cells but negatively correlated with ECP and Th2 cells in patients with severe asthma." (PMID 34692717, 2021). "Serum MBD2, ECP and MPO levels were increased in patients with severe asthma compared to those with asthma (P < 0.001) and HCs (P < 0.001), as well as in patients with asthma compared to HCs (P < 0.001)." (PMID 34692717, 2021). "Interestingly, in this study, we also found that MBD2 was negatively correlated with Th2 cells and ECP in patients with severe asthma." (PMID 34692717, 2021).